MMP9 (matrix metallopeptidase 9)
Diseases named in the same sentence as MMP9 in open-access papers (continued):
Sharing a sentence is not in itself a finding about the gene and the disease.
myocardial infarction (continued). "In animal studies as well, both MMP-9 and chymase activities in the infarcted cardiac tissues were significantly increased in the acute phase just after myocardial infarction in hamsters." (PMID 36289761, 2022). "Plasma MMP-9 levels were also seen to be sharply increased just after acute myocardial infarction in patients." (PMID 36289761, 2022). "IR and ECMO increased while Impella reduced levels of MMP-9 in the myocardial infarct zone, circulation, and renal cortex." (PMID 33782857, 2022). "Multiple research projects established the relation between MMP-9 and post-myocardial infarction (MI) heart failure and mortality prediction." (PMID 35629221, 2022). "Apigenin ameliorated acute myocardial infarction in rats via inhibiting MMP-9 and inflammatory reactions." (PMID 35410418, 2022). "Macrophage-derived matrix metalloproteinase 9 (MMP-9) can directly or indirectly improve wound healing and remodeling after myocardial infarction." (PMID 35924237, 2022). "MMP-9 is particularly important to healing as its depletion leads to defective inflammation, worsening the outcome of experimental myocardial infarction." (PMID 36271425, 2022). "Thus, MMP-9 might be associated with the plaque rupture of coronary arteries, and its activation by chymase might also play an important role in the pathogenesis of myocardial infarction." (PMID 36289761, 2022). "In contrast to MMP-2 and MMP-9 where myocardial infarction (MI) induced increase of their levels/activities, MMP-28 levels decreased post-MI." (PMID 33923282, 2021). "For example, MMP-2 and MMP-9 levels are spatiotemporal modulated after a myocardial infarction or end stage heart failure, and play important roles resulting in tissue remodeling." (PMID 34571830, 2021). "In the early phase of myocardial infarction, MMP‐9 release is stimulated, as it cleaves mediators derived from neutrophils and dying cardiomyocytes." (PMID 31932967, 2021). "SMYAD reduced the expression of heart failure markers and fibrosis markers (collagen I, MMP9, and TNFα) in the heart tissue of model animals after myocardial infarction." (PMID 34367308, 2021). "On one hand, platelet activation, as occurs in myocardial infarction, results in mutual platelet and monocyte co-stimulation, extracellular matrix metalloproteinase inducer expression and secretion of monocyte MMP-9." (PMID 33579197, 2021). "MMP-9 evaluated in the first day of admission for acute myocardial infarction (STEMI and NSTEMI) was the best predictor for the primary end-point." (PMID 34362217, 2021). "The seed node is MMP9, and its protein content and enzyme activity in platelets of myocardial infarction are significantly increased." (PMID 34433871, 2021). "As a consequence, it appears that MMP-9 plays a critical role in the stability/instability of the coronary artery plaques and development of myocardial infarction during CAD." (PMID 32429880, 2020). "Remodeling of the myocardial extracellular matrix requires proteolysis, and various studies have shown that MMP-2 and MMP-9 are prominently overexpressed after myocardial infarction." (PMID 32354131, 2020). "Although MMPs levels were not examined here, others have recently described in a model of lifelong exposure to BPA a decreased recovery after myocardial infarction associated with adverse cardiac remodeling due to increased MMP2 and MMP9 expression." (PMID 32144343, 2020). "MMP-9 levels also vary between patients with acute myocardial infarction (AMI) and unstable angina pectoris (UAP); serum MMP-9 levels are higher in patients with ST segment elevation myocardial infarction (STEMI) than in those with non-STEMI (NSTEMI) or UAP." (PMID 33082709, 2020). "Thereby, MMP-9 deletion improved left ventricular function following acute myocardial infarction in mice after seven days." (PMID 32486211, 2020). "Typhaneoside regulates IL-6 and TNF-α as well as MMP-2 and MMP-9 in rats with heart failure after myocardial infarction." (PMID 31201434, 2020).
myocardial infarction (continued). "Because a decrease in myocardial infarct size indicates increased survival of myocardial tissue, it is assumed that MMP9 is potentially involved in cell death mechanisms, thus ablation of MMP9 improved survival of the myocardium." (PMID 32170070, 2020). "Studies have reported elevated levels of MMP9 mainly in patients and animals with acute myocardial infarction (AMI) and acute coronary syndrome (ACS)." (PMID 31935243, 2020). "Curcumin treatment inhibits both MMP-2 and MMP-9 through its potent antioxidant action, promoting cardiac repair and ameliorating cardiac dysfunction following myocardial infarction." (PMID 31205590, 2019). "MMP-9 inhibition leads to a lower incidence of myocardial rupture after acute myocardial infarction and lowers left ventricular dilation due to less collagen reorganization in the infarcted area in mice." (PMID 31205590, 2019). "Curcumin pretreatment was proved to reduce MMP-2 and MMP-9 expression in extracellular matrix degradation after myocardial infarction, by inhibiting the expression of angiotensin II." (PMID 31205590, 2019). "Our study is the first to report the effect of curcumin nanoparticle pretreatment on MMP-2 and MMP-9 expression in myocardial infarction." (PMID 31205590, 2019). "Aerobic exercise increased levels of serum netrin-1, myocardial netrin-1, and the DCC receptor and reduced the expression of myocardial MMP2 and MMP9 proteins, to improve the degree of fibrosis following myocardial infarction in rats." (PMID 30789913, 2019). "In future experimentation on mammalian models of myocardial infarction, it would be interesting to test specific combinations of MMPs (such as MMP9 and MMP13), as well as restricting the period of intervention to that of the inflammatory period only." (PMID 29740050, 2018). "We found that plasma LPA and MMP-9 levels were correlated positively (r = 0.31, P < 0.05) and both elevated significantly in patients with acute myocardial infarct (AMI)." (PMID 28496416, 2017). "Previous studies have reported a significant correlation between MMP-9 with coronary artery disease and outcomes after acute myocardial infarction." (PMID 28977831, 2017). "Our study showed that increases in value of MMP-9 levels were associated with increased WMIS, which is closely related to the area of acute myocardial infarction." (PMID 29285294, 2017). "Elevated serum levels of MMP-9 has been observed during the acute phase of myocardial infarction with its maximum concentrations in the culprit coronary artery rather than systemic circulation." (PMID 26843213, 2016). "Previous experimental studies showed that MMP-9 plays a key role in cardiac remodeling and contributes to chamber dilation and excessive collagen accumulation in both aging hearts and hearts post-myocardial infarction 14,15." (PMID 27276393, 2016). "Macrophages are an important source of MMP-9 during acute myocardial infarction and, for instance, MMP-9-knockout mice show a reduced rupture rate and attenuated ventricular dilation during myocardial infarction." (PMID 26112171, 2015). "Left ventricular remodeling following acute myocardial infarction was also shown to be suppressed by decrease in MMP-9 level via inhibition of the renin-angiotensin system." (PMID 26551785, 2015). "Abundance of MMP-9 is increased in several cardiovascular diseases including hypertension, atherosclerosis and myocardial infarction." (PMID 26692905, 2015). "Enhanced expression of EMMPRIN was shown on the surface of circulating monocytes in acute myocardial infarction (AMI), compared to stable angina patients, and the expression was associated with increased plasma MMP-9 activity." (PMID 25191702, 2014). "Patients with acute myocardial infarction (MI) exhibit increased expression of MMP-9 mRNA in blood monocytes." (PMID 25153995, 2014). "MMP-9 knockout mice showed increased myocardial protection and attenuated remodeling after experimental acute myocardial infarction." (PMID 23533637, 2013).
myocardial infarction (continued). "Our previous study demonstrated that SalB inhibited matrix MMP-9 activity in rat heart with myocardial infarction and ameliorated cardiac remodeling." (PMID 23533637, 2013). "And also chymase-dependent MMP-9 activation was important in the pathophysiology of myocardial infarction reperfusion and fibrosis." (PMID 23533637, 2013). "MMP2 and MMP9 are considered to play a pivotal role in myocardial remodeling in a number of cardiovascular diseases, including myocardial infarction (MI) and ischemic and idiopathic dilated cardiomyopathy (DCM)." (PMID 23710440, 2013). "Following myocardial infarction (MI), matrix metalloproteinase-9 (MMP-9) levels increase, and MMP-9 deletion improves post-MI remodeling of the left ventricle (LV)." (PMID 22778955, 2012). "Although the association between MMP-9 and alpha-2 macroglobulin has been previously reported, this is the first time that alpha-2 macroglobulin is associated with MMP-9 in the myocardial infarction setting." (PMID 22778955, 2012). "Previous studies showed that plasma MMP-9 level was increased in patients with acute coronary syndromes and acute myocardial infarction." (PMID 28348691, 2012). "The frequency of MMP-9 (-1562C>T) SNP in acute myocardial infarction is higher than controls and related with the complexity of coronary lesion." (PMID 28348691, 2012). "It was reported that up-regulation of MMP-9 was found during the first two weeks after myocardial infarction." (PMID 20735854, 2010). "In an animal model of angiotensin II-induced myocardial fibrosis, a matrix metalloproteinase-9 (MMP-9) knockout mouse model of myocardial infarction, and a mouse model of aging, M2 macrophages accumulate in large numbers and promote fibroblast activation and collagen synthesis and secretion." (PMID 40881586, 2025). "However, under certain conditions, like myocardial infarction or heart failure, MMP-9 knockout mice can show differences in cardiac remodeling and function." (PMID 39466144, 2025). "MMP-9 was also showed a reduction in accordance with a previous study of myocardial infarction." (PMID 38175709, 2024). "In addition, MMP-9 plasma levels correlate with myocardial infarction (MI) mortality, left ventricular (LV) remodeling and dysfunction in patients." (PMID 38660518, 2024). "Increased levels of MMP9 have also been reported in induced myocardial infarction in mice." (PMID 37512106, 2023). "Additionally, plaque destabilization was boosted through the increase in expression of matrix metalloproteinase (MMP)-2 and MMP-9 which was evident in blood samples derived from male patients with acute myocardial infarction." (PMID 37943388, 2023). "On the other hand, doxycycline could not reduce scar thinning and compensatory LV hypertrophy, despite having decreased MMP-2 and MMP-9 activity in a model of acute myocardial infarction with LV dysfunction." (PMID 35893744, 2022). "In addition, salvianolic acid A, a novel MMP-9 inhibitor, is widely used to treat hypertension, coronary artery disease, and myocardial infarction." (PMID 35410418, 2022). "In terms of the association between cardiac disease and MMP-9, MMP-9 might be profoundly involved in cardiac remodeling immediately after myocardial infarction." (PMID 36289761, 2022). "In the case of studies on the effect of lycopene on changes induced by myocardial infarction (MI) in a rat model, it was noticed that it suppressed the increase in MMP-9 and type I collagen expression, and inhibited p38 activation and decreased collagen levels in the periinfarct zone." (PMID 35216071, 2022). "NLRP3 inflammasome activation mainly occurs in cardiac fibroblasts during myocardial remodeling and repair, activates IL-1β release and pyroptosis in cardiac fibroblasts after myocardial infarction (MI).A significant increase in expression of pyroptosis and MMP9 in cardiac fibrosis in diabetes." (PMID 35509275, 2022). "Neutrophils and macrophages are the early primary sources of MMP-9 after myocardial infarction." (PMID 35410418, 2022).
myocardial infarction (continued). "Plaque rupture or erosion also induces myocardial infarction, and ruptured plaques are characterized by a large lipid-rich core, a thin fibrous cap and many inflammatory cells, such as macrophages, which express MMP-9." (PMID 36289761, 2022). "Moreover, in MMP9 knockout mice, enhanced cardiac protection after ischemia-reperfusion-induced myocardial infarction was reported, while MCP1 was proposed to play a major role in the onset of cardiovascular disease." (PMID 36077021, 2022). "Myocardial TNF-α was correlated with MMP-9 activity in a mouse model of myocardial infarction." (PMID 35372112, 2022). "Downregulation of MMP-9 activity in circulation is essential for HF patients since high levels of this enzyme are related to heart fibrosis, microvascular complications, peripheral arterial dysfunction, acute myocardial infarction, and unfavorable prognosis." (PMID 36547460, 2022). "Moreover, citrate synthase activity has been shown to decrease after myocardial infarction and be partially regulated by MMP-9." (PMID 34517822, 2021). "In accordance with what is reported in the present study, other studies on the subject showed high serum levels of MMP-9; furthermore, the presence of such elevated serum levels of MMP-9 has been shown to result in a high and independent risk of increased risk of CVD and myocardial infarction." (PMID 33810003, 2021). "A relationship between MMP-9 and inflammation has also been suggested in myocardial infarction and MMP-9 knockout may reduce inflammatory cytokines by suppressing inflammatory cell infiltration." (PMID 34064140, 2021). "For example, the MMP-9 global knock-out mouse, when subjected to experimental models of myocardial infarction, exhibited increased survival with improved cardiac repair and reduced fibrotic remodeling, which is similar to the phenotype found in macrophage MMP-9 overexpressing transgenic mice." (PMID 34992607, 2021). "Moreover, exosomes or extracellular vesicles from cancers, inflammatory diseases, or even myocardial infarction carry MMP9 and are involved in extensive biologic process of effects as a key biomarker." (PMID 33498689, 2021). "Other studies reporting prognostic relevance of MMP-9/TIMP‐1 ratios in a comparable setting of myocardial infarction were conducted in serum, which might explain the disparity our findings." (PMID 31932967, 2021). "Interestingly, in a study on the effect of pharmacological inhibition of MMP-9 on the outcome of acute myocardial infarction, an unexpected detrimental role of MMP-9 inhibition was also observed." (PMID 32645949, 2020). "Several other studies have reported robust associations between MMP-9 level and the subsequent risk of cardiovascular complications, such as cardiovascular mortality and nonfatal myocardial infarction." (PMID 33214686, 2020). "Indeed, it was found that CD36 (a phagocytic marker in macrophages) was reduced post-myocardial infarction in animals treated with an MMP-9 inhibitor but increased post-myocardial infarction in MMP-9 knockout mice." (PMID 31461880, 2019). "Although this hypothesis should be further demonstrated, previous reports have demonstrated that intracoronary administration of adult stem cells induces the downregulation of metalloproteinases in myocardium (MMP2 and MMP9) after myocardial infarct." (PMID 25964098, 2015). "Here, we investigated whether expression of MMP-9 and its inhibitors in blood mononuclear cells and plasma were related to depressive symptoms in patients with a recent myocardial infarction (MI)." (PMID 25153995, 2014). "Their results suggested that MMP-9 plays an important role in ischemia-reperfusion-induced myocardial infarction and that MMP-9 could be a target for prevention or treatment of acute ischemic myocardial injury." (PMID 21219642, 2011).
myocardial infarction (continued). "MMP-9 concentrations are increased in the setting of several chronic inflammatory diseases, and MMP elevations are associated with abdominal aortic aneurysm rupture and acute myocardial infarction." (PMID 21600051, 2011). "Moreover, in mice, targeted deletion of MMP-9 attenuated collagen accumulation, which was correlated with decreased infiltration of neutrophils and macrophages in resolving experimental myocardial infarction." (PMID 15642145, 2005). "Their model was validated against dynamics of inflammation and collagen content after myocardial infarction and then applied to predict how the strength or timing of perturbations to TGF-β or MMP9 can modulate the kinetics of post-MI fibrosis." (PMID 37443814, 2023). "After post-myocardial infarction (MI), the stimulated cardiomyocytes secrete large amounts of MMP-9 as well as change the intracellular structure, myofilament and cytoskeleton." (PMID 36432152, 2022). "Along with cytokines variety of matrix metalloproteinases (MMPs) participate in cardiac remodeling post-MI, out of many MMPs especially MMP-9 is the widely-studied MMP in HF after myocardial infarction." (PMID 35405389, 2022). "This hypothesis is supported by the significant association between the CTG repeat with MMP9, which is known to be a non-specific biomarker that has for instance been linked to cardiac remodeling after myocardial infarction, inflammation, and DMD." (PMID 36352383, 2022). "Markers including matrix metalloproteinase-9 (MMP-9) and tissue inhibitor of metalloproteinase-1 are prevalent in individuals with obstructive sleep apnea (OSA), hypertension, myocardial infarction, and heart failure." (PMID 40136392, 2025). "After myocardial infarction (MI), there is a significant upsurge in the levels of matrix metalloproteinases (MMPs) in the heart, particularly MMP-2 and MMP-9, with MMP-2 expression exceeding that of MMP-9 by over 30 times." (PMID 39532649, 2025). "For instance, Dan-Shen injection exerts anti-inflammatory effects by decreasing the expression of MMP2, MMP9, and myeloperoxidase (MPO) in a rat model of post-myocardial infarction." (PMID 38794213, 2024). "In all cases of myocardial infarction, median serum levels of MMP-3 (stromelysin), MMP-9, PAPP-A, TIMP-1 were 14.11 pg/ml, 58.6 pg/ml, 1.3 μg/ml, 93.85 pg/ml respectively whereas the mean serum MCP-1 was 650.57 ± 625.42 pg/ml." (PMID 39351476, 2024). "In animal models of myocardial infarction, heightened levels of tumor necrosis factor (TNF) within the myocardium directly correlate with increased production of local MMP-9 and MMP-2." (PMID 39432214, 2024). "Colchicine reduced mRNA and protein expression of MMP2 in vitro, mitigated mRNA expression of MMP-3, MMP-9, and MMP-10 in aortas of mice and abolished the relative mRNA expression of MMP-9 in infarct area of myocardium after myocardial infarction in mice." (PMID 38001470, 2023). "A recent study found that Icariin attenuated myocardial apoptosis following myocardial infarction by inhibiting apoptosis and CD147/MMP-9 pathway." (PMID 35410418, 2022). "MMP-9, located in tertiary granules, is one of the most extensively studied members of the MMP family in myocardial infarction." (PMID 35410418, 2022). "The present study assessed the effects of systemic melatonin administration on the prognosis of patients with acute myocardial infarction (AMI) successfully treated with primary percutaneous coronary intervention, and to examine the effects on MMP-9 levels." (PMID 35407517, 2022). "Eligible literatures reporting MMP-9 rs3918242 and susceptibility to MI were searched in PubMed, Cochrane Library, CNRI, and VIP using keywords such as “MMP-9”, “matrix metallopeptidase-9” and “myocardial infarction”, “acute myocardial infarction”, “AMI”, and “polymorphism”." (PMID 35075377, 2022).